ENSG00000258354 (microRNA 3180-1)
Gene: Long non-coding RNA gene on chromosome 16 (14,909,887 to 14,911,345, reverse strand). Ensembl gene ENSG00000258354.
Gene Ontology:
Biological process: miRNA-mediated post-transcriptional gene silencing